ORAI3 (ORAI calcium release-activated calcium modulator 3)
Diseases named in the same sentence as ORAI3 in open-access papers (continued):
Sharing a sentence is not in itself a finding about the gene and the disease.
lung carcinoma (8 papers, 2013 to 2023). "Here, we confirm the association of the Orai3 expression with invasive adenocarcinoma, micropapillary and solid predominant subtypes, in a large cohort of patients of lung cancer." (PMID 27835593, 2016). "Studies have shown that Orai3 plays an essential role in lung cancer, with one study revealing that immunostaining of Orai3 was overexpressed in lung cancer tissues compared to nontumorous ones, and was linked to a high tumour grade." (PMID 37259313, 2023). "As for ORAI channels, very recently, Ouadid-Ahidouch’s group demonstrated clearly the involvement of ORAI3 in the enrichment of the CSC population by cisplatin treatment in lung cancer cell models, which, in turn, induces resistance to cisplatin." (PMID 36142596, 2022). "This analysis also showed that overall survival was greater in individuals with a lower Orai3 expression, thus suggesting that Orai3 is a prognostic factor for lung cancer outcome." (PMID 34768857, 2021). "In our current study, we are the first to analyze the evolution of Orai3 expression in lung cancer tissues and cell lines during the course of chemotherapy, and to further investigate the relationship between Orai3 and CSCs." (PMID 34065942, 2021). "The role of Orai3 in cell proliferation and calcium homeostasis in lung cancer cell lines was previously reported by our group." (PMID 27835593, 2016). "The compound named “B” decreases the expression of both Orai1 and Orai3 in NCl-H460 lung cancer cell line, and tumour growth in vivo." (PMID 27835593, 2016). "Several studies have reported the involvement of Orai3 in the complex machinery of carcinogenesis including breast, prostate and lung cancer." (PMID 27835593, 2016). "Multivariate regression analysis revealed that high expression of Orai3 is an independent prognostic factor for lung cancer outcome, as the tumour stage." (PMID 27835593, 2016). "In lung cancer, we have previously reported an overexpression of Orai3 in a small cohort of adenocarcinoma (N=60), and its role in cell proliferation and Ca2+ influx in lung cancer cell lines." (PMID 27835593, 2016). "We demonstrate that Orai3 expression is up-regulated in lung cancer tissues, correlates with high tumor grade, and Orai3-mediated Ca2+ entry is crucial to NSCLC cell proliferation." (PMID 24058448, 2013). "To further clarify the mechanism by which Orai3 knockdown impacts the cell cycle of lung cancer cells, we analyzed the expression of the main cell cycle regulatory proteins by Western blotting." (PMID 24058448, 2013). "ORAI3 is also involved in chemoresistance to cisplatin in both breast and lung cancer cell lines." (PMID 36142596, 2022). "Therefore, the objectives of our study were to determine Orai3 expression in lung cancer tissue samples and to establish its role in cell proliferation and survival using two NSCLC cell lines representing the most common malignant lung tumor." (PMID 24058448, 2013). "In the present study, we found that Orai3 silencing suppressed Akt phosphorylation in both cell lines suggesting that the proliferative effect of Orai3 is, in part, attributed to the Akt signaling pathway in lung cancer cells." (PMID 24058448, 2013). "Thus, the combinational use of cisplatin with mibefradil could overcome ORAI3-relative resistance, as demonstrated in breast or lung cancer models." (PMID 36142596, 2022). "In the past, several groups used 2APB (50 μM) to demonstrate Orai3 activation as a functional SOCE channel in breast and lung cancers." (PMID 34885048, 2021). "In this context, we suggest that Ca2+ entry through Orai3 may control cell cycle progression by regulating expression of cyclins and CDKs in NCI-H23 and NCI-H460 lung cancer cells." (PMID 24058448, 2013).
pancreatic cancer (6 papers, 2019 to 2025). "As Orai3 is overexpressed in pancreatic cancer tissue and is associated with poor prognosis, we next analyzed the expression of MARCH3 and MARCH8 in pancreatic cancer samples (Fig. EV4B,C)." (PMID 41023307, 2025). "Taken together, our NFATc1 gain and loss-of-function studies in six pancreatic cancer cell lines confirm the dichotomous regulation of Orai3 by NFATc1." (PMID 41023307, 2025). "Dichotomous control by NFATc1 defines cell state-specific roles of the Ca2+ channel Orai3 in pancreatic cancer." (PMID 41023307, 2025). "In invasive and metastatic pancreatic cancer cells, NFATc1 induces Orai3 lysosomal degradation by transcriptionally enhancing MARCH8 E3-ubiquitin ligase." (PMID 41023307, 2025). "Using lysosomal and proteasomal degradation inhibitors, we observed that NFATc1 induces lysosomal degradation of Orai3 in both invasive and metastatic pancreatic cancer cells." (PMID 41023307, 2025). "Surprisingly, NFATc1 acts as a bimodal regulator in metastatic pancreatic cancer cells by inducing both Orai3 transcription and Orai3 protein degradation." (PMID 41023307, 2025). "Our investigation into the mechanisms behind Orai3 protein degradation began with the observation that NFATc1 promotes Orai3 degradation in invasive and metastatic pancreatic cancer cells." (PMID 41023307, 2025). "The dual regulation of Orai3 by the same transcription factor NFATc1 underscores a complex pathway in pancreatic cancer cells that controls disease progression and clinical outcomes." (PMID 41023307, 2025). "The bimodal regulation of Orai3 by NFATc1 in invasive and metastatic pancreatic cancer cells led to the characterization of Orai3 protein degradation machinery." (PMID 41023307, 2025). "A previous study from our group revealed a critical role of Orai3 channel in regulating pancreatic cancer development and metastasis in vivo." (PMID 41023307, 2025). "Further, we have identified and characterized MARCH8 as an important regulator of Orai3-driven pancreatic cancer metastasis." (PMID 41023307, 2025). "An earlier study from our group demonstrated that Orai3 forms a functional SOCE channel in pancreatic cancer cells and regulates key hallmarks of oncogenesis." (PMID 41023307, 2025). "By harnessing the epigenetic differences in the promoter of MARCH8 E3 ubiquitin ligase, the transcription factor NFATc1 drives Orai3 transcription and protein degradation, regulating pancreatic cancer in context-dependent manner." (PMID 41023307, 2025). "Further, we demonstrated that Orai3 is transcriptionally upregulated in human pancreatic tumor samples as compared to normal patient samples." (PMID 41023307, 2025). "We reported that Orai3 is transcriptionally upregulated in pancreatic tumor samples compared to normal pancreatic samples." (PMID 41023307, 2025). "Elevated expression of Orai3 has been observed in various human cancers, including breast, prostate, and pancreatic cancer." (PMID 37759448, 2023). "The emerging pathophysiological role of Orai3 has been reported in various solid cancers, such as breast, prostate, lung, colorectal, and pancreatic cancer." (PMID 37759448, 2023). "Here, we evaluated the contribution of Orai3 to pancreatic cancer development and found that Orai3 silencing drastically decreases tumorigenesis in vivo." (PMID 34885048, 2021). "In pancreatic cancer, ORAI3 and STIM1 (key components of store operated calcium entry—SOCE) have been shown to be required for TGF-β-dependent SNAIL transcription and TGF-β signaling has already been associated with stroma-mediated drug resistance." (PMID 32629766, 2020). "Importantly, we demonstrate that MARCH8 restricts pancreatic cancer metastasis by targeting Orai3 degradation, thereby highlighting the pathophysiological importance of this signaling module." (PMID 41023307, 2025). "Importantly, the dichotomy in Orai3 regulation highlights an intricate pathway in pancreatic cancer cells that can control disease outcomes." (PMID 41023307, 2025).
pancreatic cancer (continued). "Orai3 is overexpressed in a large proportion of pancreatic tumors and pancreatic cancer cell lines." (PMID 34885048, 2021). "Based on this study and our data, it can be hypothesized that Orai3 can form hetero-multimeric SOCE channels in pancreatic cancer cells." (PMID 34885048, 2021). "Considering that Orai3 expression is inversely associated with the PC patients’ survival time and it is overexpressed in a certain proportion of pancreatic tumors, Orai3 appears to be an attractive therapeutic target, at least in the cases where its expression is elevated." (PMID 34885048, 2021). "Furthermore, the presence of an increased Orai3 expression, leading to the assembly of more Orai1/Orai3 channel complexes can increase the resistance to apoptosis, as has been suggested in the context of pancreas carcinoma." (PMID 30935064, 2019). "The dual nature of Orai3 regulation by NFATc1 depends on the non-metastatic v/s metastatic nature of pancreatic cancer cell lines." (PMID 41023307, 2025). "To delineate the role of NFATc1 in regulating Orai3 expression and function, we chose six human pancreatic cancer cell lines: MiaPaCa-2 and BxPC-3 (non-metastatic), PANC-1 and AsPC-1 (invasive), and CFPAC-1 and SW1990 (metastatic)." (PMID 41023307, 2025). "Our data demonstrate that NFATc1 positively regulates Orai3 transcription in non-metastatic pancreatic cancer cells." (PMID 41023307, 2025). "Orai3 channel function has also been found to be remodeled in cancer cells, as Orai3 knockdown enhances SOCE in pancreatic cancer cells whereas attenuates Ca2+ influx in non-tumoral cells." (PMID 34768857, 2021). "We demonstrate that NFATc1 drives Orai3 transcription in non-metastatic pancreatic cancer cells." (PMID 41023307, 2025). "Interestingly, the NFATc1 overexpression and NFAT inhibition studies in pancreatic cancer cell lines showed a surprising dichotomy in the regulation of Orai3 by NFATc1 in non-metastatic v/s invasive and metastatic cells." (PMID 41023307, 2025). "Therefore, both siRNA-mediated NFATc1 knockdown and competitive inhibition of NFAT display the dichotomous regulation of Orai3 in non-metastatic v/s metastatic pancreatic cancer cells." (PMID 41023307, 2025).
colon cancer (5 papers, 2016 to 2023). "The colony-forming ability and cell migration capacity of tumor cells were impaired after treatment with siHIF-1α and siHIF-2α, as well as siOrai3, thus indicating that HIF-1/2α promote Orai3 up-regulation, which, in turn, supports colon cancer progression." (PMID 34768857, 2021). "In addition, increased expression of Orai3 may indicate a poor prognosis in colon cancer." (PMID 37047790, 2023). "Further analysis in tumor samples from murine colon cancer xenograft models and patients have reported that hypoxia increases HIF-1/2α expression concomitantly with enhanced Orai1 and Orai3 expression and SOCE." (PMID 34768857, 2021). "Recently, human colon cancer cells have been shown to present an increase of SOCE, related to an increase in TRPC1, Orai1, Orai2, Orai3 and STIM1 expressions." (PMID 27102434, 2016).
non-small cell lung adenocarcinoma (5 papers, 2013 to 2022). Type of epithelial lung cancer arising from glandular origin. "Our observations agree with those found in non-small cell lung adenocarcinoma, where Orai3 was evidenced to regulate cell proliferation and cell cycle progression by activating Akt." (PMID 32392840, 2020). "Association between elevated ORAI3 expression, enhanced ORAI3-based SOCE and high proliferation levels was also reported for non-small-cell lung adenocarcinoma." (PMID 32733237, 2020). "Importantly, we found that Orai3 contributes to non-small cell lung adenocarcinoma cell proliferation and cell cycle progression likely through Akt pathway." (PMID 24058448, 2013). "However, Orai3 is over-expressed in tissues from 60 patients presenting non small cell lung adenocarcinoma versus non tumoral adjacent tumoral tissues." (PMID 24058448, 2013). "In order to highlight the mechanisms, by which Orai3 through the SOCE regulates proliferation and cell cycle of non-small cell lung adenocarcinoma, we analyzed, using Western blot, Akt activation when Orai3 is silenced." (PMID 24058448, 2013). "Higher Orai3 expression, elevated noncanonical Orai1/Orai3 channel formation and controlled proliferation via cell cycle progression of non-small-cell lung adenocarcinoma." (PMID 36612099, 2022).
non-small cell lung carcinoma (5 papers, 2013 to 2022). A group of at least three distinct histological types of lung cancer, including non-small cell squamous cell carcinoma, adenocarcinoma, and large cell carcinoma. "Recently, a new compound targeting calcium release-activated calcium (CRAC) channels including Orai1 and Orai3 channels has been developed by Rhizen pharmaceuticals for the treatment of the non-small cell lung cancer (Patent US 2011/0112058 A1,)." (PMID 27835593, 2016).
triple-negative breast carcinoma (5 papers, 2018 to 2024). An invasive breast carcinoma which is negative for expression of estrogen receptor (ER), progesterone receptor (PR), and human epidermal growth factor receptor 2 (HER2). "Altogether, our data reveal a negative role of AA in the cancer hallmarks of the MDA-MB-231 triple negative breast cancer cells, and these observed harmful effects of AA are exacerbated when Orai3 expression is silenced." (PMID 32392840, 2020). "Intriguingly, we found that ORAI3 is over-expressed in the mesenchymal subtype of triple-negative breast cancer." (PMID 30754719, 2019). "Leflunomide and Teriflunomide inhibit SOCE in triple-negative breast cancer cells overexpressing Orai1, but not in cells overexpressing Orai3." (PMID 38541682, 2024). "However, ORAI3 silencing suggested that ORAI3 is not a regulator of HIF1α after hypoxic exposure in MDA-MB-468 Basal-A triple negative breast cancer cells." (PMID 30754719, 2019).
cardiac hypertrophy (4 papers, 2017 to 2022). "ORAI3 pharmacologic or molecular (siRNA) neutralization inhibits protective GSK3β phosphorylation, impairs early adaptive cardiac hypertrophy and accelerates HF." (PMID 35406812, 2022). "Our group highlighted a TNFα/TNFR2-dependent signaling leading to ORAI3-dependent Ca2+ channel activation promoting early adaptive cardiac hypertrophy (ECH) and resistance to oxidative stress in rats subjected to isoproterenol infusion or abdominal aortic banding." (PMID 35406812, 2022). "It has been demonstrated that ORAI3 plays an important role in patients with cardiac hypertrophy." (PMID 34926685, 2021).
breast tumors (3 papers, 2019 to 2024). "ORAI3, predominantly found in estrogen-positive breast tumors, promotes tumor cell division and cell cycle progression, underscoring the potential of ORAI3 as a biomarker of worse prognosis." (PMID 38256136, 2024). "The same study places Orai3 as an important player in tumorigenesis in vivo, since the growth of breast tumors was significantly reduced by Orai3 knockdown before the transfer to the recipient mice with severe combined immunodeficiencies (SCID)." (PMID 30935064, 2019).
dilated cardiomyopathy (3 papers, 2020 to 2022). Cardiomyopathy which is characterized by dilation and contractile dysfunction of the left and right ventricles. "Very recently it was briefly reported that cardiomyocyte-specific deletion of Orai3 causes dilated cardiomyopathy in mice at 4 months of age and the cardiac remodeling was more aggravated in younger mice during aortic banding." (PMID 32354146, 2020).
rheumatoid arthritis (3 papers, 2021 to 2024). A chronic, systemic autoimmune disorder characterized by inflammation in the synovial membranes and articular surfaces. "In support of this model, new findings have demonstrated that Orai3 expression is increased in CD4+ T cells from patients with rheumatoid arthritis and psoriatic arthritis and that silencing of Orai3 reduces tissue inflammation in a human synovium adoptive transfer model." (PMID 36803766, 2023). "Likewise, we have found that reduced IKAROS expression in T cells from patients with rheumatoid arthritis results in increased activity of the arachidonic acid–regulated calcium ARC channel due to increased expression of ORAI3 and T cell activation in the synovial environment." (PMID 38885295, 2024). "Here the authors show that there is increased expression of ORAI3 in T cells from patients with rheumatoid arthritis and that the transcription factor IKAROS negatively regulates the ORAI3 promoter, indicating a regulatory loop that can control auto-reactivity of T cells in these patients." (PMID 33568645, 2021).
heart failure (2 papers, 2019 to 2024). Inability of the heart to pump blood at an adequate rate to meet tissue metabolic requirements. "Using intramyocardial injection of siRNA, Orai3 was in vivo knockdown during EACH to evaluate its protective activity in heart failure." (PMID 30988334, 2019). "Orai3 deletion also results in dilated cardiomyopathy and heart failure in mice, while Orai1 suppression results in reduced cardiomyocyte fractional shortening and heart failure in zebrafish." (PMID 39574715, 2024).
hepatoma (2 papers, 2018 to 2023). "A recent study showed that Orai1 and Orai3 stimulated cell growth in Human Embryonic Kidney 293 cells, human hepatoma cells (Huh-7) and HeLa cells independently on their ion-conducting properties." (PMID 30123430, 2018). "In hepatoma cells, ORAI1 and STIM2 adapter protein were the predominant forms, while in HepaRG cells, transcription of ORAI3 and STIM1 was much higher, as revealed in RNAseq dataset and by real-time PCR." (PMID 37189460, 2023).
leukemia (2 papers, 2021). A malignant (clonal) hematologic disorder, involving hematopoietic stem cells and characterized by the presence of primitive or atypical myeloid or lymphoid cells in the bone marrow and the blood. "In contrast, in leukemia, high levels of Orai3 were detected in Tipifarnib-sensitive myeloid cells and resistant cells expressed lower Orai3 levels." (PMID 34065942, 2021). "An interesting finding has been reported in tipifarnib-sensitive leukemia and multiple myeloma cell lines where Orai3 is responsible for tipifarnib-mediated Ca2+ overload, which, in turn, plays an essential role in the cytotoxic effects of tipifarnib." (PMID 34768857, 2021).
multiple myeloma (2 papers, 2021 to 2022). "Orai3 expression has been shown to be elevated in leukemia/multiple myeloma cell lines sensitive to tipifarnib when compared to a resistant myeloma cell line." (PMID 35685639, 2022). "Studies performed in the acute myeloid leukemia cell line U937 and the multiple myeloma cell line 8226 have provided evidence for a role of Orai3 in tipifarnib-induced altered Ca2+ homeostasis." (PMID 34768857, 2021).
oropharyngeal squamous cell carcinoma (2 papers, 2023 to 2025). "In this study, we explored the effects of Orai3 in the progression and stemness of oral/oropharyngeal squamous cell carcinoma (OSCC)." (PMID 37759448, 2023). "Orai3 is enriched in CSCs and promotes stemness via the Orai3–ID1 (Orai3 inhibitor of DNA binding 1) axis in oral/oropharyngeal squamous cell carcinoma (OSCC)." (PMID 40806720, 2025).
pancreatic adenocarcinoma (2 papers, 2021 to 2024). "In addition, Orai3 has also been associated with different cancer hallmarks, such as cell migration, proliferation, colony formation, or cell survival in colorectal cancer and pancreatic adenocarcinoma cells." (PMID 34768857, 2021). "In colorectal cancer and pancreatic adenocarcinoma cells, the overall functional role of Orai3 in SOCE is the classically identified modulation of SOCE, as Orai3 knockdown in these cells has been found to increase SOCE." (PMID 34768857, 2021).